IL1B (interleukin 1 beta)
Diseases named in the same sentence as IL1B in open-access papers (continued):
Sharing a sentence is not in itself a finding about the gene and the disease.
infection (continued). "IL-1α and IL-1β are pro-inflammatory cytokines with similar biological properties, produced and released at the early stages of the immune response to infections." (PMID 36680273, 2023). "Based on prior investigations, one of the main factors that can prevent infection and improve the host’s survival is the production of some cellular mediators and proinflammatory cytokines IL-1β, IFN-γ, etc." (PMID 37249978, 2023). "Clearance of these bacteria from the breast relies on a rapid and strong innate immune response, including the secretion of cytokines such as IL-1β and IL-6 and chemokines such as IL-8, which attract neutrophils to the site of infection." (PMID 38003112, 2023). "The Evans blue units, TNF-α and IL-1β levels were significantly increased in the infection groups compared with the control group; however, their levels were significantly decreased in the ABZ plus calycosin treatment group." (PMID 36341547, 2023). "Host cell infection following MAP infiltration caused an increase in the secretion of proinflammatory cytokines, such as IFN-γ, TNF-α, and IL-1β, through the upregulation of pathways related to the immune response in the MLN of the IP group at 6 weeks PI." (PMID 36795721, 2023). "Infection of ATG5fl/fl-LysM-Cre BMDMΦ resulted in an increase of IL-1β or IL-1α cytokine levels for both R. typhi and R. rickettsii (SS)." (PMID 37819111, 2023). "Infection with Staphylococcus aureus, as well as infection of macrophages with Salmonella typhimurium, Shigella flexneri, Legionella pneumophila, and Pseudomonas aeruginosa, all induce IL-1β secretion." (PMID 37366985, 2023). "High levels of CXCL10/IP-10 and IL-1β were observed in the nasal wash fluid and lungs of the primary infection groups, but the levels were lower in reinfection animals." (PMID 36633406, 2023). "The IL-1β secretion was also detected at a MOI of 4 up to 48 hours after infection with SARS-CoV-2 at the same target cells." (PMID 37920468, 2023). "In comparison, in influenza (genus Influenza A/B/C/D) infection, the cytokines IL-1β, IL-4, IL-5, IL-6, IL-10, IL-12, IL-13, TNF-α, and IFN-γ are relevant to immune cell interaction in figures." (PMID 36851285, 2023). "Results from the present study showed il-1β and tnf-α expression peaks at 3 and 6 h post infection followed by a gradual decrease in the later sampling point." (PMID 37629124, 2023). "Inflammatory cytokines, TNF, interleukin 6 and 1 β (IL-6, and IL-1β) levels increase over the course of infection in specific tissues where pathogen-specific T cells are present." (PMID 36911729, 2023). "It is also known that during infection, immune system upregulates the concentration of main pyrogenic cytokines such as IL-6, IL-1β and TNF-α that mediate the fever response." (PMID 37849757, 2023). "As can be shown, following CsA infection in mouse lung tissue, IL-1β and IL-6 mRNA gene expression was dramatically increased, while IL-10 mRNA gene expression was markedly decreased." (PMID 38259457, 2023). "Inhibition of caspase 1 via SC-236 resulted in lower expression of IL-1β on the mRNA and the secreted protein after infection with E. coli." (PMID 37697284, 2023). "Outliers with elevated biomarkers observed in both pre-infection specimens included IL-1β (N=1 participant), suPAR (N=2), MCP-1/CCL2, sCD163, and CRP (N=3), TNFα (N=9) and/or leptin (N=23)." (PMID 37461626, 2023). "Overall, IL-1β was most significantly upregulated in the rHLJ0504 infection group within 7 dpi, whereas the content of IL-1β was very low in the rSHG19 infection group." (PMID 40303711, 2023). "Chicks' immune systems are significantly activated by infection with Salmonella Enteritidis, resulting in an acute immunological emergency and excessive production of pro-inflammatory factors, including IL-1β, IL-6, and TNF-α." (PMID 37990191, 2023). "This study showed that PbA-infected mice exhibited an increase in TNF-α, IL-1β, and IL-6 expression levels in the brain at day 13 post-infection." (PMID 37730604, 2023).
infection (continued). "BMmacs derived from Tln1fl/fl and Tln1Δmye mice displayed similar levels of induced Tnf, Il1b, Il6, and Il23a transcripts after infection with C. rodentium." (PMID 38102166, 2023). "Our assays showed that infection of Beclin1fl/fl BMDMΦ with R. typhi or R. rickettsii (SS) produced lower IL-1β or IL-1α cytokine levels, as compared to that of R. montanensis." (PMID 37819111, 2023). "It has also become apparent that IL‐1β and other inflammatory DAMPs released by apoptotic cells can activate the immune system during infection, akin to pyroptosis." (PMID 37846472, 2023). "For instance, in vivo treatment of hybrid tilapia with ghrelin promotes expression level of il1b in the liver and kidney after 5 h and 10 h of infection with Aeromonas hydrophila and inhibited tnfa mRNA in the liver at 10 h and kidney at 5 h." (PMID 37238114, 2023). "In the fetal amniotic fluid, infection with either Pru or RH induced high levels of IFNγ, IFNβ, IL‐1β, and IL‐10 as compared to saline controls." (PMID 37259639, 2023). "Del2R infection significantly increased the expression of IL-1β and TNF-α mRNA by approximately 20-fold at 12 and 20 hpi, compared with ASFV-WT." (PMID 37566637, 2023). "ELISA result showed that the IL-1β production was reduced in Caspase-1-/- BMDMs compared with that in WT BMDMs during infection." (PMID 37457695, 2023). "Infection with M. ulcerans and treatment with extracellular vesicles containing mycolactone revealed that the production of IL-1β by human macrophages occurred in a mycolactone-dependent manner." (PMID 37910490, 2023). "Similar results were also obtained when IDV infection was used instead of poly(I·C) stimulation with significant decreases of IL-1β, IL-8, and iNOS mRNAs loads." (PMID 36692289, 2023). "The level of transcription factor occupancy of the promoter region of TNF-α and IL-1β in T. marneffei-infected NCOR2-013 overexpressing macrophages at 24 h post-infection were detected." (PMID 37845378, 2023). "In our study, during both experiments (Genogroup I and Genogroup IIa infections), only koi carp showed up-regulation of IL-1β post-infection." (PMID 37465154, 2023). "By secreting chemokines such as IL-8, epithelial cells direct immune cells to sites of infection and simultaneously secrete other cytokines IL-6 and IL-1β to activate inflammatory immune responses of both the innate and adaptive immune systems." (PMID 37240735, 2023). "The production of IL-1β begins early in the course of infection and is considered to be one of the main mediators of inflammation." (PMID 36835218, 2023). "In a mouse model infected with Pseudomonas, the intrapulmonary levels of inflammatory cytokines (TNF-α, IL-1β, and IL-6) and neutrophils were the highest on day 3 of infection." (PMID 36982713, 2023). "TNF-α, IL-1β, and IL-6 levels showed a significant positive correlation with the severity of infection (r = 0.660, 0.539, and 0.495, respectively)." (PMID 37068081, 2023). "We found that IL-6 and IL1β in the infection group were much higher than those in the control group by ∼7 fold and ∼17 fold, respectively." (PMID 40303727, 2023). "We observed that infection of ATG5fl/fl BMDMΦ with R. typhi or R. rickettsii (SS) produced significantly lower levels of IL-1β or IL-1α cytokine, as compared to that of R. montanensis." (PMID 37819111, 2023). "In this study, we detected the increased presence of serum cytokines IL-6, TNF-α, and IL-1β after the infection." (PMID 37256132, 2023). "TNF-α and IL-1β display bimodal patterns of stimulation recognized as essential factors for recruiting phagocytes and initiating the immune response at the infection site." (PMID 37569767, 2023). "Together, NLRP3 inflammasome activation and its downstream effectors GSDMD, IL-1β and IL-18, shelter against potential infections and help to maintain intestinal homeostasis." (PMID 37891577, 2023).
infection (continued). "Previous studies have shown that MFN2 acts as a major regulator of the immune response by binding to NLRP3 and promoting IL-1β secretion after infection with the virus." (PMID 36968589, 2023). "IL-1β, in turn, is an inflammatory cytokine that, in addition to mediating immune responses during infection and inflammation, has a role in chronic and acute autoinflammatory diseases." (PMID 37018291, 2023). "Anakinra provides the advantages of potentially better regulated physiological responses and opportunity to quickly discontinue IL-1β blockade in case of infection." (PMID 36596811, 2023). "Specifically, we assessed IL-1β and IL-8 production after 24 h infection of vaginal epithelial cells with C. albicans in the presence or absence of RBG and pRBG." (PMID 37375053, 2023). "Prominent examples include VE/DE genes that encode IL1B and IDO1, suggesting that VE/DE genes are relevant to infection and disease progression." (PMID 37333188, 2023). "As expected, the intracellular levels of ROS were increased after infection (LPS-dependent) or inflammation (IL-1β/TNFα) stimuli." (PMID 37443798, 2023). "Interleukin-1β (IL-1β) is a mediator of immunity produced by monocytes and macrophages during infection and is essential to the host response against pathogens." (PMID 36905446, 2023). "Intracellular infection or stimulation can activate the inflammasome and induce the maturation and secretion of inflammatory cytokines, such as IL-1β, prompting a series of innate immune responses." (PMID 37109536, 2023). "High levels of cytokines and chemokines, including CXCL10/IP-10 and IL-1β, were observed in the nasal wash fluid of the primary infection group (DMEM-BA.1), but these were lower in reinfected animals." (PMID 36633406, 2023). "The expression of caspase 1 and IL-1β was then assessed via immunoblotting or ELISAs in cell extracts or supernatants at 18 and 24 h post-infection (p.i.)." (PMID 37375491, 2023). "The results in serum showed that the level of pro-inflammatory cytokine IL-1β and IL-6 dramatically increased and the level of anti-inflammatory cytokine IL-10 considerably dropped after CsA infection." (PMID 38259457, 2023). "Subsequently, we determined the expression of TNF-α and IL-1β, the representative inflammatory factors in the small intestine during the early stage of infection by qPCR, and the results were consistent with the pathological results of the sections." (PMID 37585413, 2023). "HIV-1Q23-BG505 infection also resulted in IL-1β secretion in a CARD8-dependent manner, suggesting that CARD8-dependent inflammasome activation is conserved across HIV-1 strains." (PMID 37417868, 2023). "The secretion of TNF-α, IL-1β, and IL-6 can be up-regulated in response to infection with B. bronchiseptica, as these cytokines play a role in the immune response to the bacteria." (PMID 38066337, 2023). "Next, we aimed to investigate if liver damage upon RVFV cl13 infection is mediated by a dysregulation of the IL-1 family members IL-1β and/or IL-1RA as it has been shown before for poly(I:C) treatment." (PMID 37720217, 2023). "IL-1β, an essential component of the host’s defense mechanism against infection and injury, is known to play a pivotal role in regulating the inflammatory response." (PMID 37521462, 2023). "Conversely, infection with MAB-R triggered secretion of IL-1β (≈30.000 pg/mL) that was dramatically reduced following treatment with amikacin (≈30 pg/mL)." (PMID 36674717, 2023). "Previously published data demonstrated increased activation of the NLRP3 inflammasome, caspase-1, caspase-5, IL-1β, IL-18 and gasdermin D after infection of C. acnes-infected nucleus pulposus tissue." (PMID 36761775, 2023). "Mature and functionally active 17 kDa IL-1β species can be generated by caspase-1 cleavage, and released at sites of infection/injury to regulate diverse physiological responses." (PMID 36519759, 2023).
infection (continued). "IL-1β is a pro-inflammatory cytokine produced by immune cells such as macrophages and monocytes in response to infections or injuries, which can regulate immune responses, including fever, inflammation, and activation of other immune cells." (PMID 37920268, 2023). "At 1 h, the relative expression levels of IL-1β by HGECs in the experimental groups were significantly lower than that in the control group, which means that ZA inhibited the expression of IL-1β by HGECs at the early stage of infection." (PMID 37056703, 2023). "In groups receiving a bacterium plus parasite, the expression level of IL-1β was significantly higher at the end of the infection period than at the middle (P<0.0001)." (PMID 36779192, 2023). "The culture supernatants were then analyzed for the secreted levels of IL-1β at 24 h post-infection." (PMID 37266012, 2023). "Previous studies involving cp-BVDV infection in macrophages have shown that IL-1β secretion is stimulated 24 h post-infection due to the activation of NFкB and that IL-1β maturation is mediated by the NLRP3 inflammasome." (PMID 37515181, 2023). "Interleukin-1β (IL-1β) is a powerful proinflammatory cytokine and has an important role in host defense against injury and infection." (PMID 37763806, 2023). "LPS also activates monocytes and macrophages to produce interleukin-1 beta (IL-1β), an early cytokine mediator in murine injury and infection which mediates hypothermia, cytokine storm, and inflammation." (PMID 36650454, 2023). "Results of infection with ∆yopK also showed reduced IL-1β release when the BMDMs were treated with CA, although the decrease was not significant." (PMID 37787552, 2023). "The relative mRNA expression levels of IL-1β and IL-8 were measured after 3 h of infection and in the presence of 0.125% Auraguard." (PMID 37237883, 2023). "The infection of cells by EV71 can activate the NLRP3 inflammasome, which then causes the creation and release of proinflammatory cytokines including active IL-1β." (PMID 38249297, 2023). "Pre-sensitization of macrophages with exosomes prior to infection was shown to increase IL-1β and IL-6 levels." (PMID 37841240, 2023). "ST infection markedly improved the mRNA relative expression levels of inflammasome biomarkers including Caspase-1, IL-1β and IL-18 compared with the control group (p < 0.05)." (PMID 37893938, 2023). "Cytokine assay confirmed that as the infection time prolonged, the levels of inflammatory cytokines (especially IL-6 and: IL-1β) decreased, while anti-inflammatory cytokines (especially IL-4) increased." (PMID 38076459, 2023). "In a previous study, our research group reported that the secretion of IL-1β was caspase 1-dependent during infection of bovine macrophages with the NADL cp-BVDV strain." (PMID 37515181, 2023). "Nlrc4-/- neutrophils incubated with MCC950 responded the same as C57BL/6 neutrophils, i.e., MCC950 inhibited IL-1β following infection with PAO1 or ExoS ADPRT expressing mutants." (PMID 37730693, 2023). "We also observed a significant rise in the levels of inflammatory factors, such as IL-18 and IL-1β, in the serum of infected mice, with the ZB-1 group showing significantly higher levels than the ZB-1Δirp2 group, peaking 24 hours after infection." (PMID 37511208, 2023). "Infection with virulent strains of NDV causes a strong immune response, resulting in the release of large quantities of inflammatory factors such as IL-1β, IL-6, IL-18, and IFN-β." (PMID 37608944, 2023). "Macrophages are critical sensor cells that detect infection and induce inflammatory responses by producing cytokines such as TNFα and IL-1β." (PMID 37819792, 2023). "The infection with Mtb increased the production of IL-1β, IL-1α, IL-12, Interferon γ (IFN-γ), TNF, and the Granulocyte macrophage colony stimulating factor (GM-CSF)." (PMID 37375056, 2023). "Following infection, the proinflammatory cytokines IL-1β, TNFα, and IL-6 were upregulated in the olfactory bulb and hippocampus at DPI-4." (PMID 38006064, 2023).
infection (continued). "Accordingly, in vivo infection with ASFV ∆MGF505-7R leads to elevated IL-1β production and compromised pathology and virus replication." (PMID 37631977, 2023). "Significantly higher HA-specific IgG responses were measured in nasal swabs in animals immunized with Ad-HA/NP+Ad-IL-1β compared to Ad-HA/NP only or pH1N1 infection and had higher IgA responses compared to the controls." (PMID 37153548, 2023). "Activation of Inflammasome by AIM2 is responsible for IL‐1β release following infection from various DNA viruses such as vaccinia virus and adenovirus." (PMID 37773712, 2023). "In general, the expression of pro-inflammatory cytokines such as il1β and tnfα was upregulated in all three segments of intestine except for il1β in the posterior intestine at 24 h and tnfα in the anterior intestine at 24 and 48 h post-infection." (PMID 37759501, 2023). "With murine macrophages (peritoneal and BMDMs), the release of IL-1β upon infection with Mtb, BCG and M. abscessus, and Il1b transcription with Mip was NOD2 dependent." (PMID 37262021, 2023). "Meanwhile, SE infection also induced intestinal inflammation by upregulating inflammatory-related cytokine TNF-α mRNA levels, pro-inflammatory cytokines IL-1β and NF-κB mRNA levels in the ileum at the early infection stage." (PMID 37391807, 2023). "The skin and posterior-intestine of challenged fish responded quite similarly, with il-1β, il8 and mmp9 as the most highly induced genes, which provides evidence that an inflammatory response is activated upon infection with T. maritimum." (PMID 37731496, 2023). "Infection of macrophages with H2O- or IPTG-treated BL21/pEmpty or BL21 expressing other OI-14-genes induced similar levels of IL-1β." (PMID 37041208, 2023). "As the key players in the regulation of inflammatory processes, the expression levels of IL-1β and IL-18 were measured in vivo and in vitro to explore the relationship between YT strain infection and inflammation." (PMID 37063902, 2023). "In the late stage of infection, the mRNA expression of IL-1β in the β-glucan + APS group and the enrofloxacin group was significantly lower than in the other groups." (PMID 37894188, 2023). "In this study, we found that the protein levels of the inflammasome signaling protein caspase-1, ASC, IL-1β and IL-18 were elevated during COVID-19 infection and remained elevated even after the active infection was over." (PMID 37168848, 2023). "IL-1β plays a crucial role in controlling infection and injury, but excessive and uncontrolled production can lead to chronic inflammation and contribute to the development of inflammation." (PMID 38066337, 2023). "The colonic cytokine contents were analyzed, and it was detected that CR infection promoted the pro-inflammatory factors IL-1β, TNF-α, IL-6, and IL-17A (p < 0.01), as well as the anti-inflammatory factors IL-4 (p > 0.05) and IL-10 (p < 0.01)." (PMID 37111225, 2023). "Nos2 and Il1β mRNA levels increased upon S. japonicum infection, reached a peak at 6 weeks post‐infection (p < 0.05), and then decreased." (PMID 37430471, 2023). "At 4–6 dpi, IL-1β mRNA levels in the rHLJ0504 infection group were 1.62–5.13 times higher than those in the rHLJ-D279N group." (PMID 40303711, 2023). "The mRNA expression levels of IL-6, IL-18, IFN-α, IFN-β, and ISG-15 were up-regulated during EV-G/YN23/2022 infection, while IL-1β, TNF-α, IFN-λ3, and IRF-7 maintained in relatively constant levels, and no cytokines were significantly reduced." (PMID 37632087, 2023). "Pro-inflammatory cytokines (including IL-1β, IL-6, and IL-8) are necessary to initiate an inflammatory response during infection." (PMID 38026634, 2023). "The abundance of IL-8, a chemokine that mediates neutrophil chemotaxis to sites of infection and tissue damage, exhibited a similar pattern as IL-1β in the colon and suggests that BC50 partly restores the negative impact of BZA on colon IL-1β and IL-8 status." (PMID 37841323, 2023).